IL6 (interleukin 6)
Diseases named in the same sentence as IL6 in open-access papers (continued):
Sharing a sentence is not in itself a finding about the gene and the disease.
ileus (11 papers, 2013 to 2025). Decrease in peristalsis in the absence of a mechanical bowel obstruction. "No statistical difference was observed between pressures or the existence of an ileus, but the maximum levels of IL‐6 and IL‐10 detected in some patients reflect a pressure difference." (PMID 37636200, 2023). "In a murine (C3H/HeOuJ) endotoxin-induced ileus model, IL-6 inhibition (IL-6R antibody) prevented late ileus development." (PMID 35805922, 2022). "By supplementing with probiotics or synbiotics before and after the operation, it is possible to alleviate post-operative ileus by reducing the levels of pro-inflammatory molecules such as tumor necrosis factor-α, interleukin-6, C-reactive protein, and nitric oxide." (PMID 37373843, 2023). "Overall, the results show that while IL-6 is often upregulated in models of ileus or feeding intolerance, the effects of IL-6 on gastrointestinal motility are unclear and may be context- and species-dependent." (PMID 35805922, 2022). "The local inflammatory status may have a significant modulating role and correlations between ileus and increased systemic levels of proinflammatory cytokines (IL-1β, IL-6 and TNF-α) were also identified." (PMID 24137421, 2013). "In the postoperative ileus (POI) model, EA at ST36 decreased TNF-α and IL-6 concentration in serum and MPO activities in the intestine." (PMID 35095910, 2021). "The pro-inflammatory cytokines TNF-α and IL-6 in adipose tissue and liver in obese mice fed a high-fat diet and the levels of TNF-α and IL-6 in postoperative ileus rats can be reduced by ginsenoside Rb1." (PMID 32020864, 2020). "In a rat with postoperative ileus, ginsenoside Rb1 reduces serum concentration of TNF-α, IL-1β, IL-6, and IL-10, indicating its anti-inflammatory effect." (PMID 30402203, 2018). "In rats with postoperative ileus, expression of TNF-α, IL-1β, IL-6, and IL-10 is reduced by Rb1 in ileum tissue, along with gastrointestinal transit increased, indicating a potent anti-inflammatory effect." (PMID 30402203, 2018). "In ileus animals, levels of KC, MCP-1 and IL-6 were elevated at 24 h of POI, in both WT and CB1–/– mice as compared to corresponding normal or sham control groups (P<0.01)." (PMID 23844009, 2013). "Investigations into the role of inflammatory mediators in the development of ileus have been somewhat biased, in that most investigators check a handful of classic inflammatory mediators, such as IL6 and TNF-α, without examining other inflammatory mediators." (PMID 35805922, 2022). "In contrast, in another study, IL-1β, along with IL-6 and procalcitonin, was higher in patients with prolonged POI compared to patients who did not develop ileus following surgery for colorectal carcinoma." (PMID 35805922, 2022).
kidney cancer (11 papers, 2020 to 2024). Primary or metastatic malignant neoplasm involving the kidney. "In our previous study, we also found that PTGS2, PIK3CA, IGF1R, and IL6 commonly caused kidney cancer and inflammation, and by suppressing these genes, we can reduce the severity of kidney cancer and inflammation." (PMID 38666938, 2024). "Therefore, highly elevated IL-6 levels may be associated with increased intratumoral immunosuppression in patients with kidney cancer." (PMID 36497467, 2022). "Studies have revealed that cancer-related fibroblasts are involved in enhancing the migratory properties of the prostate, kidney, and kidney cancer, by secreting several stimulating factors such as IL-6 or CCL3 that activate STAT3." (PMID 36230984, 2022). "We also found that IL6 exhibited the opposite expression pattern in some subtypes of brain and kidney cancers." (PMID 35246158, 2022). "Our previous in silico protein–protein interaction (PPI) and molecular docking studies revealed that the isoquercitrin compound could trigger potential cancer-causing gene targets, such as IGF1R, PIK3CA, IL6, and PTGS2, which can regulate kidney cancer and inflammation." (PMID 38666938, 2024). "Thus, we investigated whether there were differences in treatment outcomes depending on IL-6 levels in patients with kidney cancer who were administered first line Pembro/Axi." (PMID 36497467, 2022). "Our previous study predicted using protein-protein interaction (PPI) and molecular docking analysis that the isoquercitrin compound can control kidney cancer and inflammation by triggering potential gene targets of IGF1R, PIK3CA, IL6, and PTGS2." (PMID 38666938, 2024). "The overexpression of SIGIRR in RCC cells attenuated IL1-induced NFKBIZ activation, with a trend of effect on IL6, PD-L1, and ICAM1 induction, suggesting that SIGIRR manipulation may be beneficial to block IL1 in kidney cancer." (PMID 35814450, 2022). "In advanced kidney cancer with TTM treatment in a phase II trial, stable disease was achieved in 31% of patients, and proangiogenic molecules of interleukin-6, interleukin-8, vascular endothelial growth factor, and basic fibroblast growth factor in serum decreased to realise anti-angiogenic effects." (PMID 36186457, 2022).
lichen planus (11 papers, 2012 to 2025). A chronic, recurrent, pruritic inflammatory disorder of unknown etiology that affects the skin and mucus membranes. "Previously, cytokines such as IFN-γ and IL-6 have been studied in specimens of lichen planus, indicating that these proinflammatory cytokines are produced not only by activated T lymphocytes, but also by altered keratinocytes." (PMID 27649154, 2016). "Although the exact mechanism remains unclear, it has been proposed that dupilumab's inhibition of IL-4 and IL-13 may indirectly downregulate IL-6-driven Th2 responses, which are elevated in patients with lichen planus and may contribute to disease persistence." (PMID 40718341, 2025). "Lichen planus is assumed to represent a delayed hypersensitivity reaction, in the course of which cytokines, including IL-6, control the proliferation and differentiation of cytotoxic T lymphocytes which attack the epidermis and cause apoptosis of the undifferentiated keratinocytes." (PMID 26535093, 2015). "Up-regulation of intercellular adhesion molecule-1 (ICAM-1) and cytokines associated with Th 1 immune response, such as interferon (IFN)-gamma, tumour necrosis factor (TNF)- alpha, interleukin (IL)-1 alpha, IL-6 and IL-8, may also play a role in the pathogenesis of lichen planus." (PMID 22980383, 2012). "Our findings demonstrate a statistically significant increase in the expression of IL-1β, IL-6, and RIPK3 in the skin biopsy samples of SJS/TEN patients compared to those of lichen planus (LP) patients and normal controls." (PMID 39941220, 2025). "Our findings highlight that IL-1β, IL-6, and RIPK3 play pivotal roles in these disease processes, with significantly elevated expression levels observed in the skin of SJS/TEN patients compared to those with lichen planus (LP) or normal controls." (PMID 39941220, 2025). "A significant difference in IL-6 expression was observed in the epithelium of pooled samples from SJS/TEN patients (average immunofluorescence [IF] intensity: 299 a.u.), lichen planus (LP) patients (average IF intensity: 241 a.u.), and normal controls (average IF intensity: 204 a.u.)(p < 0.0001)." (PMID 39941220, 2025). "Our findings indicate that IL-1β, IL-6, and RIPK3 may play potential roles in the disease process, with significantly elevated expression levels in the skin of SJS/TEN patients compared to those with lichen planus (LP) or normal controls." (PMID 39941220, 2025).
meningoencephalitis (11 papers, 2013 to 2025). Inflammation of the meninges and brain, generally secondary to an infectious cause. "These lesions consisted of a meningoencephalitis with moderate to severe perivascular cuffing associated with the presence of NiV RNA, IL-6 and TNF mRNA." (PMID 40125323, 2025). "Meningoencephalitis presumably caused by Enterovirus infection elicits robust intrathecal pro-inflammatory cytokine pattern, with statistically higher levels of IL-6, TNF and IL-17." (PMID 26286516, 2015). "Here, we report a patient with RP with meningoencephalitis with severe brain damage and elevated levels of IL-6 in the CSF." (PMID 34128872, 2021). "The present case highlights the importance of CSF IL-6 levels in the screening RP-related meningoencephalitis." (PMID 34128872, 2021). "Meningoencephalitis composed of high and low cellularity displayed similar levels of IL-6 in the CSF, indicating that the secretion of this cytokine is probably independent of the cell influx to the CNS." (PMID 26286516, 2015). "In this respect, the evolved strain also resembled the neurotropic fungus C. neoformans, which likewise induces local TNFα and IL-6 responses in the brain, correlating with its presence in the CNS and the progression of meningoencephalitis." (PMID 25356907, 2014). "brucei-infected mice studies are in agreement with these results where a correlation between IL-6 presence in the brain with meningoencephalitis as well as astrocyte activation was observed." (PMID 24194772, 2013). "The current study investigated the profile of CSF IL-6, total protein, total white cell changes, and activation of astrocytes in the lead up to pathological lesions indicative of meningoencephalitis in this monkey model." (PMID 24194772, 2013). "In this regard, levels of interleukin-6 (IL-6) and tumor necrosis factor alpha (TNF-α) were measured in cerebrospinal fluids from patients with meningoencephalitis." (PMID 26286516, 2015). "In the present research, we described histopathological changes, viral dissemination, glial reaction, and expression of TNFα, TGF-β, INF-γ, IL-6, IL-10, IL-12p40, IL-12p70, MCP-1, and NO in the brains of young adult mice after Maraba virus-induced meningoencephalitis." (PMID 32294697, 2020). "The diads IL-10/IFN-γ and IL-6/IL-17 are present only in undiagnosed meningoencephalitis patients regardless of cellularity." (PMID 26286516, 2015). "Late-stage disease is characterized by parasite invasion of meninges and choroid plexus with IL-6, known to be involved in BBB modulation, also playing a role in the accompanied activation of astrocytes in the brain and eventual inflammation of the brain (meningoencephalitis)." (PMID 24194772, 2013). "The levels of IL-6, IL-10, IFN-α and IFN-γ were significantly higher in the CSF samples from patients suffering of viral meningitis or meningoencephalitis as compared to noninfectious CNS diseases." (PMID 26569288, 2015).
Middle East respiratory syndrome (11 papers, 2020 to 2024). A viral respiratory infection that is caused by the MERS coronavirus (MERS-CoV), which most often manifests with moderate to severe respiratory symptoms, including productive cough and shortness of breath, which can progress to pneumonia and acute respiratory distress syndrome. "In the research of the Middle East respiratory syndrome (MERS), caused by another coronavirus (MERS-CoV), cytokine genes of IL-6, IL-1β, and IL-8 can be markedly high." (PMID 33585031, 2021). "Elevation of IL-6 was associated with mortality in infection with the similar coronavirus, MERS-CoV, responsible for Middle East Respiratory Syndrome (MERS)." (PMID 32992282, 2020). "Impaired organ function and high death rate were also directly related to increased immunological response, including high levels of the proinflammatory cytokine IL-6 in Middle East Respiratory Syndrome (MERS)." (PMID 37008057, 2023). "In the research of Middle East respiratory syndrome (MERS), caused by another coronavirus (MERS-CoV), cytokine genes of IL-6, IL-1β, and IL-8 can be markedly high." (PMID 32350134, 2020). "This includes the pro-inflammatory cytokines such as interleukin (IL)-1, IL-6 and tumor necrosis factor (TNF)-α, as well as the inflammatory chemokines CCL-2 and CXCL-10, which have previously been seen in other coronavirus infections such as Middle East respiratory syndrome (MERS)." (PMID 35054471, 2022). "Elevated IL-6 is a prominent and constitutive factor of CRS, just like CRS in severe acute respiratory syndrome (SARS) or Middle East respiratory syndrome (MERS) patients." (PMID 33717715, 2021).
muscular atrophy (11 papers, 2011 to 2025). "IL-6, in particular, has been implicated in skeletal muscle atrophy in preclinical disease models, a finding corroborated by our observation of increased IL-6 levels in the diaphragm." (PMID 40965630, 2025). "By reducing muscle anabolism and supply-demand balance, IL-6 has been demonstrated to cause muscular atrophy." (PMID 38233827, 2024). "The overexpression of IL-6 in transgenic mice caused muscular atrophy and increased levels of cathepsin in skeletal muscle, indicating that IL-6 is involved in the regulation of muscle protein degradation." (PMID 32493731, 2020). "In a previous study, we showed that immobilization-induced skeletal muscle atrophy is associated with the upregulation of the inflammation markers TNFα, IL-6, and IL-1." (PMID 21843349, 2011). "Systemic inflammation may trigger protein catabolism and impair the anabolic response whereby an increase in proinflammatory cytokines (e.g., TNF-α, IL-1, IL-6) is associated with muscular atrophy." (PMID 39497175, 2024). "On the one hand, excessive IL-6 can cause skeletal muscle atrophy." (PMID 34552592, 2021). "A role for both SAA1 and IL-6 in muscular atrophy was recently reported." (PMID 24651840, 2014). "It is therefore clear that STAT3 activation, mainly due to an increase in the myokine IL-6, can promote NMJ disassembly, which in turn further increases IL-6/STAT3 signalling, creating a positive feedback loop, resulting in muscular atrophy." (PMID 37828541, 2023).
pulmonary embolism (11 papers, 2021 to 2025). The obstruction of the pulmonary artery or one of its branches by an embolus, sometimes associated with infarction of the lung. "Subgroup analysis revealed that the predictive values of IL6 and IL8 were pronounced in patients with pulmonary embolism (AUC = 0.72, IL6) and septic shock (AUC = 0.77, IL8), with significantly elevated cytokine levels." (PMID 41339250, 2025). "In the sensitivity analysis of the outcome of pulmonary embolism, neither the overall immunomodulatory agents nor IL-6 antagonists significantly reduced the risk of pulmonary embolism." (PMID 34830648, 2021). "Our experiments indicate that in the acute pulmonary embolism combined with shock model, the TLR4/NF-κB/HIF-1α signaling pathway is activated, which might stimulate the upregulation on the expression of downstream Gal-3, and the release of inflammatory factors such as IL-6 and TNF-α." (PMID 40666114, 2025). "OCT was able to detect small distal pulmonary artery thrombosis in patients with a negative CT scan for pulmonary embolism and elevated thromboinflammatory markers (i.e., high D-dimer, CRP, IL-6, or ferritin)." (PMID 36873865, 2023).
pyometra (11 papers, 2015 to 2026). "Studies investigating cytokines involved in canine pyometra demonstrated that mainly interleukin 6 (IL-6) and the chemokine (C-X-C motif) ligands such as CXCL8, CXCL5, and CXCL10 are involved." (PMID 40911583, 2025). "Further investigations are required to confirm the possible correlation between nesfatin-1 and BCS, CRP, IL-6, and the presents of ovarian cysts in bitches suffering from pyometra." (PMID 39455994, 2024). "Overall, transcription levels of pro-inflammatory cytokines IL-1β, IL-6 and IL-8, and of anti-inflammatory cytokines IL-10 and TGFβ were significantly higher (p < 0.0001) in pyometra endometria than in healthy diestrous endometria." (PMID 27829462, 2016). "In conclusion, an increase in serum concentrations of IL-6 and IL-10 occurred before surgery in bitches with pyometra and 3 days after OHE in healthy control bitches undergoing elective OHE." (PMID 26410584, 2015). "Based on our result we suggest, that production of IL-6 and IL-10 is upregulated in bitches having pyometra." (PMID 26410584, 2015). "A high concentration of IL-6 in bitches with pyometra indicates an activation of the cellular immune system." (PMID 26410584, 2015). "The aim of the study was to assess changes in serum interleukin (IL)-6 and IL-10 concentrations in bitches with pyometra undergoing ovariohysterectomy." (PMID 26410584, 2015). "An increase in serum concentrations of IL-6 and IL-10 was present before surgery in bitches with pyometra and 3 days after ovariohysterectomy in healthy controls." (PMID 26410584, 2015). "In pyometra, the primary immune response is mediated by e.g. IL-6, the concentrations of which is both delayed and sustained in comparison with other cytokines." (PMID 26410584, 2015). "Compared to the presurgery concentration bitches with pyometra had decreased serum concentration of IL-6 and IL-10 3 days after OHE (P < 0.01 and P < 0.05, respectively) and 10 days after OHE (P < 0.01 for both IL6 and IL10)." (PMID 26410584, 2015). "Before surgery, bitches with pyometra had significantly higher serum concentrations of IL-6 and IL-10 than the controls." (PMID 26410584, 2015). "For this reason, the aim of the study was to assess concentrations of serum IL-6 and IL-10 in bitches with pyometra undergoing ovariohysterectomy (OHE) and compare these finding to healthy bitches undergoing elective OHE." (PMID 26410584, 2015). "In accordance, pyometra is characterized by endometrial tissue damage, infiltration by inflammatory cells, accumulation of pus, and increased expression of inflammatory mediators such as interleukins IL-1β, IL-6 and IL-8." (PMID 27829462, 2016). "Before surgery, bitches with pyometra had higher serum concentrations of IL-6 and IL-10 (149.4 (120.2–179.5) pg/ml and 53.9 (34.1–73.3) pg/ml, respectively) than the controls [1.8 (1.8–2.0) pg/ml and 21.2 (19.5–28.2) pg/ml] (P < 0.001 for both IL-6 and IL10)." (PMID 26410584, 2015). "Thus we hypothesized that in cases of canine pyometra alterations in IL-6 and/or IL-10 could be present." (PMID 26410584, 2015). "The levels of IL6 and IL10 decreased significantly in the bitches with pyometra on days 3 and 10 after surgery as also reported by others." (PMID 26410584, 2015). "Accordingly, the IL1B and IL8 genes were detected as overexpressed in pyometra group, being IL1B, IL6 and TNF overexpressed particularly in pyometra of hormone-treated animals." (PMID 26222498, 2015). "The transcription level pattern in PEH group suggests that IL-6 is probably an important cytokine involved in PEH uterine response to bacterial stimuli and can be the target for further understanding PEH inflammation in pyometra cases." (PMID 40911583, 2025). "β-hemolytic E. coli pyometra endometria had higher gene transcription of IL-1β and IL-8 and lower gene transcription of IL-6 than non-hemolytic E. coli pyometra endometria (p < 0.01)." (PMID 27829462, 2016).
pyometra (continued). "β-hemolytic E. coli pyometra endometria had higher gene transcription of IL-1β and IL-8 and lower gene transcription of IL-6 than non-hemolytic pyometra endometria." (PMID 27829462, 2016). "Interestingly, a reduction in interleukin 6 (IL-6) gene expression and macrophage migration inhibitory factor (MIF) in the uterus of cats with pyometra, as well as an increase in the endometrial immunolabeling of IL-10, was observed, suggesting the activation of anti-inflammatory defenses." (PMID 37835759, 2023). "However, hemolytic E. coli pyometra endometria had higher transcription levels of IL-1β and IL-8 and lower transcription levels of IL-6 than non-hemolytic E. coli endometria (p < 0.01)." (PMID 27829462, 2016). "A lack of consistently high concentrations of IL-6 has been reported in other inflammatory diseases in dogs such as IMHA, pyometra and cervical spondylomyelopathy." (PMID 26953797, 2016).